TGFBI (transforming growth factor beta induced)
Diseases named in the same sentence as TGFBI in open-access papers (continued):
Sharing a sentence is not in itself a finding about the gene and the disease.
glioma (continued). "Transforming growth factor-beta-induced (TGFBI) is an exocrine protein that has been proven to promote the development of glioma, nasopharyngeal carcinoma, bladder cancer and other tumours." (PMID 33553434, 2021). "In glioma, the median survival time for patients with a high expression of TGFBI was significantly shorter than that of patients showing low expressions of TGFBI." (PMID 34217310, 2021). "In a recent study, Guo Sk and colleagues showed that TGFBI was upregulated in glioma cells and played a promoting role in the growth and motility of U87 and U251 cells." (PMID 33553434, 2021). "In support of this, PDGFD and PDGFRB were positively correlated with a three-gene signature (TGFBI, IGFBP3, and CHI3L1) associated with glioma tumor cell invasion and migration and poor patient survival." (PMID 34539622, 2021). "The silencing of TGFBI in glioma and gastrointestinal cancer decreased local tumor growth and metastasis." (PMID 31514337, 2019). "Additionally, IHC staining of TGFBI expression in 58 glioma specimens revealed a positive correlation between TGFBI and HIF1α." (PMID 39346536, 2024). "To delve deeper, we assessed TGFBI expression across various glioma grades." (PMID 39346536, 2024). "Moreover, within the subset of IDH wt gliomas, higher TGFBI expression levels were correlated with worse patient survival." (PMID 39346536, 2024). "Furthermore, IHC staining on human glioma specimens confirmed a positive correlation between TGFBI and c-MYC level." (PMID 39346536, 2024). "Our examination of 58 human samples, encompassing normal (n = 11), grade II glioma (n = 11), grade III glioma (n = 7), and GBM (n = 29), highlighted a notable increase in TGFBI expression in high-grade tumors, suggesting a potential role for TGFBI in driving glioma malignancy." (PMID 39346536, 2024). "In recurrent gliomas, the mean protein level of TGFBI was higher than in primary gliomas." (PMID 35673564, 2022). "Together with its critical role in enhancing glioma growth, TGFBI level in patient serum/CSF may distinctly index TAM abundance and its functionality in glioma progress." (PMID 35673564, 2022). "High TGFBI expression promotes proliferation and migration of glioma cells." (PMID 35198102, 2022). "The results showed serum TGFBI concentrations of GBMs were much higher than healthy controls, WHO grade 2 and grade 3 gliomas." (PMID 35673564, 2022). "Next, glioma scRNA-seq datasets (GSE84465 40 and GSE148842 41) were analyzed to validate the relationship between TGFBI, TIMP1 and M2-like TAMs." (PMID 35673564, 2022). "We found a candidate molecule, transforming growth factor beta-induced (TGFBI), that was specifically expressed by TAMs and extremely low in GBM and GSC cells, and meanwhile closely related to glioma WHO grades and patient prognosis." (PMID 35673564, 2022). "We found such a candidate molecule, transforming growth factor beta-induced (TGFBI) that was specifically expressed in M2-like TAMs and extremely low in GBM and GSC cells, and meanwhile closely related to glioma WHO grades and patient prognosis." (PMID 35673564, 2022). "Similarly, IHC analysis revealed a strong positive correlation between TGFBI and CD163 in glioma patients." (PMID 35673564, 2022). "Additionally, we assessed in situ hybridizations for TGFBI and BIN1 in glioma tissue sections from IGAP." (PMID 29262845, 2017).
colon carcinoma (25 papers, 2008 to 2025). "Recent studies have found that TGFBI CpG islands are hypermethylated in adjacent normal colon tissue, with the corresponding sequences showing hypomethylation in colon cancer tissue, and that higher TGFBI levels are associated with poorer prognosis." (PMID 37388244, 2023). "Colon cancer tissues had higher levels of TGFBI mRNA, which is linked to extravasation and invasiveness." (PMID 37205191, 2023). "Secretion of TGFBI in colon cancer cells has association with cancer invasiveness and extravasation." (PMID 35083181, 2022). "But we found that TGFβ signaling associated genes TGFBR2 and TGFBI was highly expressed in MSS subtype of colon cancer, suggesting the potential inhibition of TGFβ signaling pathway in MSI subtype colon cancer patients." (PMID 31221124, 2019). "TGFBI has been identified as a member of a metastasis network in oesophageal squamous cell carcinoma, with higher expression noted in renal, gastrointestinal, and brain tumours, and linked to increased metastatic potential and poorer prognosis in colon cancer." (PMID 20041153, 2009). "Using in vitro and bioinformatics experiments, it was determined that miR-766-3p can specifically aim TGFBI and that, in colon cancer, its level was downregulated while TGFBI was elevated." (PMID 37205191, 2023). "- Overexpressed miR-766-3p promotes apoptosis of colon cancer cells and inhibits cancer progression by targeting TGFBI." (PMID 37205191, 2023). "The oncogene TGFBI was considered to target by miR-766-3p and was involved in colon cancer progression induced by miR-766-3p." (PMID 35083181, 2022). "Flow cytometry result clarified that overexpression of miR-766-3p markedly promoted cell apoptosis in colon cancer, while the upregulatory effect was suppressed by concurrently overexpressing miR-766-3p and TGFBI." (PMID 35083181, 2022). "In this study, TCGA analysis exhibited that TGFBI was dramatically overexpressed in colon cancer tissues." (PMID 35083181, 2022). "To authenticate the impacts of miR-766-3p and TGFBI on colon cancer cells, we constructed a cell line with miR-766-3p overexpression (miR-mimic + oe-NC) and a cells line with simultaneous overexpression of TGFBI and miR-766-3p (miR-mimic + oe-TGFBI)." (PMID 35083181, 2022). "MiR-766-3p overexpression dramatically restrained the TGFBI mRNA level in colon cancer cells, as measured by qRT-PCR." (PMID 35083181, 2022). "The results of cell invasion and wound healing assays indicated that miR-766-3p upregulation appreciably restrained cell migration and invasion of colon cancer cells, while such effect was weakened by simultaneously upregulating miR-766-3p and TGFBI." (PMID 35083181, 2022). "Through a conjoint analysis with related bioinformatics databases, we found that there was an interaction between miR-766-3p and TGFBI and that their expression was negatively correlated in colon cancer tissues." (PMID 35083181, 2022). "The present study confirmed that miR-766-3p targeted TGFBI to modulate malignant progression of colon cancer cells." (PMID 35083181, 2022). "The results certified that overexpression of TGFBI hindered the inhibitory impact of miR-766-3p forced expression on cell malignant behaviors and the promotive effect on cell apoptosis in colon cancer." (PMID 35083181, 2022). "The result of CCK-8 demonstrated that when miR-766-3p was overexpressed, the proliferative ability of colon cancer cells was outstandingly reduced, while this inhibitory effect was attenuated by concurrently overexpressing TGFBI and miR-766-3p." (PMID 35083181, 2022). "MiR-766-3p/TGFBI axis suppressed malignant behaviors and facilitated apoptosis of colon cancer cells." (PMID 35083181, 2022). "Some studies have shown that upregulated TGFBI can act as a tumor promoter in esophageal squamous cell carcinoma, colon cancer, gastric cancer, and bladder cancer." (PMID 34671645, 2021).
colon carcinoma (continued). "TGFBI protein was upregulated in colon cancer and clear cell renal cell carcinoma compared to normal tissues (p < 0.001) but downregulated in OV and uterine corpus endometrial carcinoma (UCEC; p < 0.001)." (PMID 34671645, 2021). "Conversely, in colon cancer, TGFBI has been shown to favour extravasation, which in turn promotes metastasis." (PMID 33080107, 2020). "A functional analysis of TGFBI in various colon cancer cell lines revealed that high levels of the protein were associated with enhanced metastasis and extravasation." (PMID 28106769, 2017). "The closely related family member TGFBI is also induced in areas of injury or cancers of the colon, ovary, lung, breast and within the injured heart." (PMID 28750100, 2017). "Immunohistochemistry has determined that human colon carcinomas manifest increased TGFBI expression." (PMID 25889002, 2015). "mRNA expression and immunohistochemistry studies have revealed that TGFBI is one of the genes overexpressed abnormally in colon carcinomas and adenomas." (PMID 25889002, 2015). "Gain of 5-hmC also occurs at TGFBI, a gene whose over-expression in colon cancer has been considered as a prognostic biomarker and target for therapy since TGFBI promotes metastasis." (PMID 26631571, 2015). "In some cases, overexpression of TGFBI in renal, pancreas or colon cancer cells induces cell migration and increases metastatic potential." (PMID 25369402, 2014). "This is supported by recent data that suggests the RGD motif of TGFBI is necessary for promoting extravasation of metastatic colon cancer cells." (PMID 22640878, 2012). "TGFBI (GENE ID:7045) itself is an extracellular matrix protein that promotes metastasis in colon cancer by enhancing cell extravasation." (PMID 20419098, 2010). "There is one report in the literature showing that overexpression of TGFBI promotes metastasis of SW480 colon cancer cells by enhancing extravasation." (PMID 18834524, 2008). "For this reason, Gao and colleagues analyzed how TGFBI affects colon cancer cells and whether miRNAs target the TGFBI gene." (PMID 37205191, 2023). "TGFBI had been found to promote metastasis via integrin αvβ5-Src axis in human colon cancer cells." (PMID 35673564, 2022). "Our experiments proposed that miR-766-3p and TGFBI had a targeting relation in colon cancer cells." (PMID 35083181, 2022). "The effect of simultaneous abnormal expression of miR-766-3p and TGFBI on the malignant phenotypes and apoptosis of colon cancer cells was studied to explore the regulatory relationship and the functional mechanism of miR-766-3p and TGFBI in colon cancer." (PMID 35083181, 2022). "MiR-766-3p was less expressed, while TGFBI was conspicuously highly expressed in colon cancer." (PMID 35083181, 2022). "In colon, TGFBI is a marker to distinguish normal mucosa from benign adenoma and colon cancer." (PMID 33408771, 2021). "A previous study also found that TGFBI was upregulated in colon cancer, promoting metastasis." (PMID 34671645, 2021). "For instance, TGFβ signaling associated genes TGFBR2 and TGFBI were both not enhanced in MSI colon cancer patients’ tissue and MSI colon cancer cell lines." (PMID 31221124, 2019). "TGFBI overexpression in colon carcinoma cells enhances their metastasis in mice in vivo." (PMID 25889002, 2015). "However, an acquired expression of TGFBI by SW480 colon cancer cells leads to a more aggressive phenotype of metastasis by favoring extravasation." (PMID 25369402, 2014). "Besides, TGFBI was notably highly expressed in colon cancer tissues in TCGA." (PMID 35083181, 2022). "In order to investigate the curcumol mechanism in inhibiting colon cancer angiogenesis through OTUB1 downregulation and TGFBI ubiquitination, we performed immunoprecipitation (IP) and Western blot analyses." (PMID 40430059, 2025). "C10_TGFBI displayed high expression of TGFBI, a structural homolog of POSTN, which was found to promote metastasis of colon cancer by enhancing cell extravasation." (PMID 38115703, 2023).
colon carcinoma (continued). "In colon cancer, BMP7 is common overregulated gene, as are TGFB2, TGFBI, and TGIF2, which might be involved in the regulation of SOX4." (PMID 39228892, 2024). "TGFBI mRNA level is higher in colon cancer tissues than in noncancer tissues." (PMID 35083181, 2022).
granular corneal dystrophy type II (25 papers, 2009 to 2025). Type II granular corneal dystrophy (GCDII) is a rare form of stromal corneal dystrophy characterized by irregular-shaped well-demarcated granular deposits in the superficial central corneal stroma, and progressive visual impairment. "We investigated the clinical and genetic features of patients with severe phenotype of granular corneal dystrophy type 2 (GCD2) associated with compound heterozygosity in the transforming growth factor-β-induced (TGFBI) gene." (PMID 33772078, 2021). "In summary, we established a human granular corneal dystrophy type 2 mouse model caused by R124H mutation of TGFBI." (PMID 26197481, 2015). "Among these stromal dystrophies, granular corneal dystrophy type 2 (GCD2) caused by a mutation in codon 124 of the TGFBI gene (R124H) is the most common condition in Japan." (PMID 26197481, 2015). "We established a granular corneal dystrophy type 2 mouse model caused by R124H mutation of human TGFBI." (PMID 26197481, 2015). "Granular corneal dystrophy type 2 (GCD2) is an autosomal dominant disorder caused by a mutation in codon 124 of the TGFBI gene that results in an arginine-to-histidine substitution (R124H)." (PMID 25853243, 2015). "Granular corneal dystrophy type 2 (GCD2), also known as Avellino corneal dystrophy, is an autosomal dominant disorder caused by a mutation in codon 124 of the transforming growth factor-beta-induced (TGFBI) gene, in which histidine replaces arginine (R124H)." (PMID 22815629, 2012). "The R124H mutation of the keratoepithelin gene (TGFBI) causes Avellino corneal dystrophy whereas the N544S mutation of this same gene gives rise to lattice corneal dystrophy." (PMID 19461933, 2009). "TGFBI‐linked corneal dystrophy is an autosomal dominant disorder, caused by mutations in the transforming growth factor β‐induced (TGFBI) gene on chromosome 5q31, while granular corneal dystrophy type 2 (GCD2) is only caused by an arginine to histidine substitution at codon 124 of the TGFBI gene." (PMID 32667742, 2020). "Classic lattice corneal dystrophy (classic LCD) and granular corneal dystrophy type 2 (GCD2) are phenotypes of p.(R124C) and p.(R124H) from transforming growth factor β-induced gene (TGFBI) variants, respectively, with autosomal dominant expression." (PMID 39858623, 2025). "Our study demonstrated that a G>A transition in Arg124His of TGFBI was responsible for Avellino corneal dystrophy in a Chinese pedigree." (PMID 22194646, 2011). "The point mutations R124C, R124H, R555W, and R555Q of TGFBI were initially found to give rise to lattice corneal dystrophy (LCD), Avellino corneal dystrophy (ACD), Groenouw type I corneal dystrophy, and Reis-Bücklers corneal dystrophy, respectively." (PMID 19461933, 2009). "Granular corneal dystrophy type 2 (GCD2, also previously called Avellino corneal dystrophy) is an autosomal dominant disorder caused by pathogenic variant p.(Arg124His) in the transforming growth factor-β-induced gene (TGFBI) on chromosome 5q31." (PMID 36980838, 2023). "Avellino corneal dystrophy (ACD) is an autosomal dominant disorder, characterized by the presence of deposits in the anterior stroma, and results from a specific mutation (R124H) in the transforming growth factor beta-induced gene (TGFBI)." (PMID 23837658, 2013). "Kim SY reported that IL-7 plays a critical role in corneal fibroblasts in granular corneal dystrophy type 2 by reducing the expression of TGF-β and TGFBI through regulation of the RNNKI/RANK signaling cascade and by regulating the expression of MT-MMP." (PMID 38455059, 2024).
colorectal cancer (24 papers, 2011 to 2026). A primary or metastatic malignant neoplasm that affects the colon or rectum. "For instance, in colorectal cancer, TGFBI overexpression is associated with high-grade tumors, enhancing cancer cell invasiveness and altering metastatic characteristics while paradoxically suppressing liver metastasis." (PMID 40430059, 2025). "In a recent preclinical study, an antibody targeting TGFBI with diagnostic and therapeutic potential was investigated in colorectal cancer models." (PMID 40082664, 2025). "Based on current research evidence, this study elucidates the molecular mechanism by which curcumol suppresses angiogenesis and metastasis in colorectal cancer through modulation of the OTUB1/TGFBI signaling pathway." (PMID 40430059, 2025). "Our findings elucidate the molecular mechanism by which curcumol exerts its anti-metastatic effects through the regulation of the OTUB1/TGFBI axis, highlighting its potential as a novel therapeutic agent for colorectal cancer treatment." (PMID 40430059, 2025). "On the other hand, it was discovered that an overexpression of miR-21-5p downregulates TGFBI, resulting in pyroptosis and the release of inflammatory factors in colorectal cancer." (PMID 37298343, 2023). "Transforming growth factor-beta-induced protein ig-h3 (TGFBI), a major TGFβ-induced protein relevant to cell adhesion, also present in the serum of patients, promotes colorectal cancer metastasis and angiogenesis." (PMID 37443766, 2023). "Nevertheless, another research considers that TGFBI induce angiogenesis in colorectal cancer, indicating the organ-specific function of TGFBI in angiogenesis." (PMID 36906534, 2023). "In colorectal cancer, TGFBI promotes metastasis via stimulating β5 integrin/Src and disconnection of VE-cadherin junctions between epithelial cells." (PMID 36906534, 2023). "TGFBI was upregulated in colorectal cancer, esophageal cancer, gastric cancer, head and neck cancer, and lymphoma." (PMID 34671645, 2021). "Collectively, we revealed that miR-21-5p induces pyroptosis in colorectal cancer via TGFBI regulation, thereby providing important mechanistic insights into its antitumor effects and expanding its potential for clinical applications." (PMID 33614494, 2020). "In renal, pancreatic and colorectal cancers, TGFBI has been reported to act as a tumor promoter, and increased TGFBI expression has been observed." (PMID 31514337, 2019). "Notably, hsa-miR-21-5p, which is upregulated in colorectal cancer, has been shown to target genes involved in apoptosis and inflammatory responses, such as TGFBI and PDCD4, both of which were also found to be downregulated in our study." (PMID 39336798, 2024). "Furthermore, four genes, ABCG2, PADI2, CA7, and TGFBI, have been verified in previous studies as potentially correlated with colorectal cancer." (PMID 28229027, 2017). "TGFBi inhibits cell adhesion and correlates with advanced metastasis in colorectal cancer." (PMID 21284875, 2011). "Mechanistic studies revealed that curcumol modulates TGFBI ubiquitination by suppressing OTUB1-mediated protein stabilization, ultimately attenuating angiogenesis in colorectal cancer." (PMID 40430059, 2025). "As expected, tumor-derived organoids highly expressed in vivo tumor-specific genes, many of which have been widely reported to be closely related to colorectal cancer progression and metastasis, such as PROCR, SCD, BMP4, CEACAM6, TESC, and TGFBI." (PMID 35484598, 2022). "Many targets of miR-675 have been proposed in different tumors, such as Twist1 and RB in hepatocellular carcinoma and colorectal cancer, CALN1 and RUNX1 in gastric cancer, TGFBI in prostate cancer." (PMID 26198047, 2016). "In conclusion, our study provides the first elucidation of the molecular mechanism by which curcumol suppresses colorectal cancer angiogenesis through downregulating OTUB1 expression, thereby blocking its deubiquitinating effect on TGFBI and promoting TGFBI ubiquitination-mediated degradation." (PMID 40430059, 2025).
colorectal cancer (continued). "LEPREL2 has previously been identified, together with TGFBI, as part of a hub of genes controlling the response to 5-fluorouracil-based chemotherapy in colorectal cancer, although the level of expression of this gene was not itself significantly different between resistant and sensitive cell lines." (PMID 39494610, 2024).